EGFR (epidermal growth factor receptor)
Diseases named in the same sentence as EGFR in open-access papers (continued):
Sharing a sentence is not in itself a finding about the gene and the disease.
tumor (continued). "Tumor-secreted REG4 can change the tumor microenvironment to facilitate cancer cell growth and metastasis by promoting macrophage polarization to M2 via activation of the EGFR/Akt/CREB pathway." (PMID 33489872, 2020). "In particular, coating of the EVs with PEG-EGFR increased their bioavailability and enhanced the EV binding to EGFR-overexpressing tumor cells, while decreasing non-specific interactions." (PMID 33105857, 2020). "Finally, compared to macroH2A1 KD Huh-7 cells, FAK KD cells exhibited a significant reduction (p < 0.01) in the mRNA levels of tumor-promoting genes CCL2, EGF, BAX, KRT19, EGFR, NOTCH1, ABL1, and SMAD3." (PMID 33182805, 2020). "Ideally, all future clinical studies targeting EGFR should include pre-/post- tissue EGFR expression, and measurement of intra-tumoral drug concentration in both enhancing and non-enhancing regions of the tumor on the MRI (magnetic resonance imaging)." (PMID 33187135, 2020). "Critically, we identified n = 4 EGFR mutations (EGFR c.2126A>C, EGFR c.2303G>T, EGFR c.2432C>T and EGFR c.2573T>G) in three individuals that were present in PFPE tumour FNA preparations but not identified in the FFPE comparator FNA samples." (PMID 31571426, 2020). "In a different study, patients with EGFR mutation showed a lack of T cell infiltration, a reduced proportion of PD-L1+/CD8+ TIL, and decreased tumor mutational burden." (PMID 33276569, 2020). "The results showed that the two anti-EGFR sdAbs significantly inhibited the tumor growth compared with the PBS and the two sdAbs as negative controls." (PMID 33023595, 2020). "Finally, we looked at introducing the EGFR and PDGFRA amplified sub-populations in different locations in the growing tumour simulations." (PMID 33120534, 2020). "Molecular analyses revealed that the tumor was negative for epidermal growth factor receptor (EGFR) mutations and anaplastic lymphoma kinase (ALK) gene rearrangements and that >90% of the tumor cells expressed programmed death ligand 1 (PD‐L1)." (PMID 32181993, 2020). "FDA approval is for patients with PD-L1 stained ≥ 50% of tumor cells, or PD-L1 stained tumor-infiltrating immune cells covering ≥ 10% of the tumor area, with no EGFR or ALK genomic tumor aberrations." (PMID 33171686, 2020). "EGFR expression and tumor perfusion were not added in this multivariable analysis, as these data were only available for a limited number of lesions." (PMID 31705176, 2020). "While there are some promising reports, neither the treatment response prediction nor the prognosis of EGFR tumours offered by these biomarkers are convincing enough to support wide clinical implementation." (PMID 33198090, 2020). "Due to the invasive phenotype and high angiogenic activity of cancer cells, the epidermal growth factor receptor (EGFR) and vascular endothelial growth factor receptor (VEGFR) are commonly overexpressed in tumor tissues and, therefore, are frequent targets for cancer therapies." (PMID 32932957, 2020). "Currently, patients with these tumor characteristics do not receive anti-EGFR mAbs due to lack of efficacy." (PMID 31705176, 2020). "The data presented here confirm that the overall acute response to EGFR-targeted NB-PS mediated PDT is not just a tumor cell specific response but a complex mixture of tumor cell responses and vascular effects." (PMID 32089747, 2020). "Indeed, EGFR- and MET-addicted tumour cells undergo a metabolic shift towards increased glycolysis and production of lactate during prolonged treatment with TKIs and onset of resistance." (PMID 33302515, 2020).
tumor (continued). "Overexpression of transforming growth factor-α (TGFα), which enhances epidermal growth factor receptor (EGFR) activation, promoted the development of hyperplasia and tumours about one and a half months earlier in STAT5-expressing mice compared to STAT5a KO mice." (PMID 32872372, 2020). "In addition, the phosphorylation of STAT3/5 and EGFR, as well as the expression of total EGFR, PKCα, TRIB3, and core pluripotency factors, were reduced in tumor tissue samples from NCI-H1975 inoculated mice treated with SAH-JGZ4." (PMID 32694521, 2020). "Although the mechanistic basis for this relationship remains unknown, variation in tumor 24-hydroxylase levels may contribute to a differential benefit of vitamin D supplementation in patients with KRAS-mutant and EGFR-mutant tumors." (PMID 32183160, 2020). "Consistently, CD99CRIII3 inhibited EGFR dimerization in wt-MDA-MB-231-originated tumor tissues, but not in shPTPN12-MDA-MB-231-originated tumor tissues." (PMID 33050232, 2020). "Growth factors such as VEGF and hepatocyte growth factor (HGF), and epidermal growth factor receptor (EGFR) have been observed to be overexpressed in many cancers including HCC, as they play a crucial role in different mechanisms involving tumor proliferation, metastasis and angiogenesis." (PMID 32722054, 2020). "In contrast to EGF, GE11 does not activate EGFR, and thus mitogenic activity of the tumor cells should be much lower." (PMID 32917034, 2020). "Lifirafenib is an investigational, reversible BRAF V600E inhibitor as well as an inhibitor of A-RAF, B-RAF, C-RAF, and EGFR that was studied in a phase I, dose-escalation trial investigating the safety and efficacy of the drug in BRAF mutant as well as RAS mutant sold tumor patients." (PMID 33182254, 2020). "As already shown in other studies that investigated anti-EGFR regimens, these activity results did not translate into similar gains in delaying tumor progression, challenging the role of PFS as surrogate endpoint for OS for this treatment." (PMID 32824490, 2020). "Moreover, novel EGFR and ALK TKIs are being used in therapy since they are effective on refractory tumor resistant to previous generations ones." (PMID 36046776, 2020). "The pathological significance of our small-molecule approach, which simultaneously reduced RAS, β-catenin, and EGFR levels, was supported by their correlated overexpression in TNBC patient tumor tissues compared with the adjacent normal mammary glands in our survey using tissue microarray." (PMID 32457491, 2020). "For mice bearing FaDu-MAPK1-WT xenografts, erlotinib treatment did not result in any change in tumor size or membranous p-EGFR signal in the tumors (vs. vehicle control, P = 0.4080)." (PMID 32351709, 2020). "Likewise, other UniCAR TMs targeting, e.g., GD2, EGFR, STn, and PSCA, were successfully radiolabeled and applied for both cancer immunotherapy and tumor visualization in mice." (PMID 32455621, 2020). "In the literature, the upregulation of PD-L1 in tumor cells is correlated with two mechanisms—the extrinsic pathway which depends on interferon gamma produced by NK and CD8+ T cells, and the intrinsic pathway which relies on the EGFR/JAK2 signaling pathway." (PMID 32872195, 2020). "Regarding the difference in local changes in EGFR immunoreactivity in patients without EGFR expression in the tumor, we compared the Tis and Tadv groups according to AJCC T grading." (PMID 32833992, 2020). "They further showed an elevated presence of HER3 in residual tumour tissue of TNBC patients not having achieved a pCR after therapy with EGFR‐targeted antibodies." (PMID 32558176, 2020). "Mig-6 is a cytosolic protein and negative feedback regulator of EGFR signaling; thus, Mig-6 can be a potential tumor suppressor." (PMID 32430054, 2020). "This suggests that EGFR is a therapeutic target for treatment of STS; which is independent of histologic subtypes, for those tumours expressing EGFR." (PMID 32002123, 2020).
tumor (continued). "EGFR was not amplified, and no mutations or deletions were found in either the patient or PDX tumours by WGS." (PMID 33053751, 2020). "In conclusion, in patients with EGFR-mutant NSCLC enrolled in this study, the presence/absence of tumor PD-L1 expression was associated with the PFS and the proportion of acquisition of the T790M mutation of EGFR after first-line treatment with EGFR-TKIs." (PMID 33255696, 2020). "EGFR activation triggers two primary intracellular signaling pathways, such as Ras/Raf/MAPK and the PI3K/Akt pathways, which enhances survival proliferation, migration and apoptosis resistance of certain tumor cells." (PMID 32592373, 2020). "Abnormally high HDAC9 expression is closely related to proliferation, invasion, and metastasis of various tumor types, and it may up-regulate genes that participate in the oncogenic Ras, VEGF, MAPK, and EGFR signaling pathways." (PMID 33552961, 2020). "Thus, we considered the option of co-targeting these two receptors by firstly testing the combinations of ipilimumab with the anti-EGFR aptamer CL4, in order to verify if they show additive effects on both tumor cells and immune cells." (PMID 32024070, 2020). "There are several emerging therapies and repurposed drugs targeting tumor-driving signaling pathways in TNBC, including epidermal growth factor (EGFR/HER1) antibodies, PI3K/AKT/mTOR, and angiogenesis inhibitors, androgen receptor (AR) antagonists, and estrogen receptor beta (ERβ) agonists." (PMID 32846967, 2020). "In TNBC, it has been suggested that AR activation alters the tumor microenvironment, hence suppressing the antitumor response and upregulating the secretion of the epidermal growth factor receptor (EGFR) ligand amphiregulin (AREG), both stimulating tumor growth and progression." (PMID 33138097, 2020). "Results of the ex vivo screening indicated an apparent MAPK/PI3K signaling pathway switch in the tumor cells based on the high sensitivity of the cells to mTOR inhibition, MEK inhibition and partial response also to antifolate abitrexate, BRAF and EGFR inhibition." (PMID 32576176, 2020). "Moreover, EGFR T790M was detectable in a prior tumor sample from patient FR069, suggesting that spatial tumor heterogeneity and subclonal events were missed by tumor sequencing, yet captured by ctDNA analyses of matched plasma samples." (PMID 32748806, 2020). "In addition, in the context of PCa, the acquisition of a hormone-refractory state was suggested to be related to an excessive activation of the EGFR axis and the downstream pathways, including PI3K-AKT and ERK, thus impinging on several tumor traits." (PMID 32069895, 2020). "Mechanistic studies showed that TE reduced tumor cell proliferation, induced cell apoptosis, inhibited metastasis via modulating multiple targets, such as molecules involved in Wnt and Src pathways, EMT and EGFR-related pathways." (PMID 33552955, 2020). "In conclusions, we identified that miR-4731 plays a tumor suppressor role in GBM cell proliferation and migration by targeting EGFR expression, and miR-4731 may act as a novel biomarker for early diagnosis or therapeutic target of GBM." (PMID 33369441, 2020). "Consideration the significantly lower EGFR expression in 22Rv1 compared to DU145, we think that the tumor suppressive activities of CMTM5-v1 in EGFR- overexpressed cells could be more effective." (PMID 32328181, 2020). "On a patient level, EGFR expression did not correlate to the geometric mean SUVpeak of all tumor lesions (> 4.2 mL)." (PMID 31705176, 2020). "In contrast to the EGFR-specific ITs, mAbs do not have the ability to kill tumor cells directly, but instead, they inhibit ligand binding, block signal transduction and inhibit EGFR gene expression." (PMID 33014289, 2020).
tumor (continued). "Hypoxia sensitive signal transduction pathways also regulate alternative splicing, resulting in tumour promoting VEGF, FGF, HGF and TGFβ signaling, ligand-independent EGFR signaling, myogenic to mitogenic conversion of insulin growth factor signaling and also specify signaling pathways use." (PMID 32536347, 2020). "Expression of p-EGFR and PKM2 in lung tumors and paired, normal, tumor-adjacent lung tissue." (PMID 32695675, 2020). "In summary, our findings revealed that genistein, a tyrosine kinase inhibitor, inhibits EGFR expression, resulting in the restriction of the Akt and JAK1/2 signaling pathways, thereby suppressing cell proliferation and inducing tumor cell apoptosis in vitro and in vivo." (PMID 32276266, 2020). "Patients treated with EGFR-TKI alone were more likely to have a N2–3 (51.4% TKI alone vs. 31.8% upfront RT; P = 0.018) and M1a (18.7% TKI alone vs. 0% upfront RT; P < 0.0001) stage tumour at diagnosis." (PMID 32298306, 2020). "The treatment of the case suggested that the brain and rib metastasis tumor were both probably driven by ALK gene rather than EGFR." (PMID 32375829, 2020). "For example, immunotherapy has been shown to improve prognosis, particularly of MSI-high tumor carrying patients, whereas anti-EGFR and 5-FU adjuvant therapies exert little and no benefit to MSI-H tumors in contrast to MSS tumors." (PMID 33363037, 2020). "It has been demonstrated that anti-EGFR antibody treatment with cetuximab and with panitumumab did not confer benefits for tumours with a mutant KRAS gene." (PMID 33183271, 2020). "The ability of mAb806 ADCs to target a conformational epitope exposed in tumor-specific conditions allows effective tumor targeting without the conventional EGFR inhibitor-mediated toxicities." (PMID 33023139, 2020). "Also, SNX1 and SNX6 facilitate the fate of epidermal growth factor receptor (EGFR) and the tumor suppression p27Kip1." (PMID 33374212, 2020). "This indicates that tumor cell population at relapse might be mainly composed of wt RAS clones, possibly opening a therapeutic window with anti-EGFR in patients who “switch” to RAS wt status in plasma at the time of disease progression." (PMID 33291569, 2020). "Screening criteria for enrolling patients will include RECIST tumor staging criteria, screening patients with tumor diameters and relative increases of 0%–20% after previous EGFR‐TKI monotherapy, and increased CEA levels after previous EGFR‐TKI monotherapy." (PMID 31918452, 2020). "The first meta-analysis included 11 studies and 2185 patients and the result just reached significance (HR 1.13, 95% CI, 1.00–1.28), implying that patients with a tumour not expressing EGFR had a better survival." (PMID 33247670, 2020). "All circulating tumour cells (detected in 13% of cases) were positive for EGFR, independent of their EMT-related phenotype." (PMID 32901137, 2020). "Notably, we observed mTOR-dependent metabolic vulnerability in tumor cells from different NSCLC subtypes, Kras- and EGFR-driven LUAD." (PMID 32943635, 2020). "The other anti-EGFR agent, the fully human IgG2 antibody panitumumab, does not show the same ability in mobilizing innate and adaptive immune cells against tumor cells." (PMID 32824490, 2020). "The epidermal growth factor receptor (EGFR)/PI3K/Akt/nuclear factor κB (NF-κB) signaling pathway plays an important role in the occurrence and development of tumors, especially in the proliferation, invasion, and metastasis of tumor cells." (PMID 33604287, 2020). "Indeed, CDDO-Me has also been shown to target cyclin D1, EGFR, and STAT3 signaling in PyMT tumor cells." (PMID 32300202, 2020). "In both discrepant cases the primary tumor harbored a KRAS mutation, thus the patients were initially stratified to receive no EGFR-antibody therapy because of the presence of a KRAS mutation." (PMID 33002027, 2020).
tumor (continued). "Similarly to other tumours, GBM is characterized by an aberrant EGFR expression and activation, leading to de-regulated downstream signalling pathways." (PMID 32823532, 2020). "SRC, ephrinB, EGFR, and HER2 signaling are inhibited by PTPN13 that limits anchorage-independent cell growth (SRC), cell proliferation (HER2 and EGFR), and also invasion and tumor aggressiveness (SRC, HER2)." (PMID 33322542, 2020). "Also, the GEM downregulated the EGFR protein level via ubiquitination in a dose-dependent manner in SCK and PANC-1 tumor lysates." (PMID 32111094, 2020). "In response to EGF, active EGFR induces N-glycosyltransferase B3GNT3 expression, leading to B3GNT3-mediated glycosylation of PD-L1, which subsequently inhibits PD-L1 degradation resulting in immunosuppression in a breast xenograft tumor model." (PMID 33159034, 2020). "Immune-based therapies are approved for use in patients with no actionable molecular tumor alterations but are not indicated for front-line use in EGFR-mutant NSCLC patients that are the subject of this review." (PMID 32292420, 2020). "One explanation for this increased sensitivity to cetuximab could be the increase in EGFR expression, which is a target of cetuximab, that was seen in LK0917 and LK1108 tumor cells cultured with CAFs." (PMID 33353547, 2020). "Based on preceding screening of EGFR and HER3 expression in primary and metastatic NSCLC tumor tissue, the CTC detection method based on these two markers has been developed and exerted the possibility to capture a larger fraction of CTCs also in combination with EpCAM in NSCLC patients." (PMID 32854390, 2020). "EGFR inhibition mimics the dual inhibition of MEK/ERK, effectively targets JunD/RSK3 and reverses the BETi resistance phenotype, again highlighting the potential of anti-EGFR therapies in treating BET-inhibition-resistant tumours." (PMID 31937753, 2020). "The mere assessment of EGFR expression at the DNA or protein level using bulk primary tumor samples has not been an ideal indicator for predicting the response to anti-EGFR drugs." (PMID 31635038, 2019). "Furthermore, we investigated the molecular effects of 213Bi-anti-EGFR-MAb treatment in LN18 and EJ28Luc tumor cells with two techniques." (PMID 31165773, 2019). "Aberrant EGFR and ERK1/2 signaling are vital in tumor cell migration, invasion, and angiogenesis." (PMID 30556643, 2019). "Furthermore, reduced tumor vascularization, reduced expression of EGFR, as well as reduced phosphorylation of Akt and ERK, will prevent tumor progression." (PMID 30987191, 2019). "Among other targetable tyrosine kinases AXL, MET and EGFR were expressed at high levels in some, but not all, tumor samples." (PMID 30881919, 2019). "The difference in tumor-growth kinetics between anti-ANG and anti-EGFR agents may warrant further exploration." (PMID 31539075, 2019). "Since the EGFR pathway represents a possible target for cancer treatment, we quantify the effect of the EGF concentration in the lymph node (eg0) on the development of the tumor." (PMID 31157216, 2019). "Similarly, there is high left-sided tumor expression of EGFR ligands AREG and EREG, which lead to high sensitivity to EGFR blockades." (PMID 30736475, 2019). "We considered a cure as sustained tumor disappearance over the 5-year period since initial chemotherapy or EGFR-TKI initiation, with no treatment for previous one year, which was defined as CR in this study." (PMID 31752884, 2019). "In patients with metastatic castration-resistant prostate cancer, a combination of everolimus and the EGFR inhibitor gefitinib has no significant anti-tumor activity." (PMID 31277692, 2019).